CUL1 (cullin 1)
Diseases named in the same sentence as CUL1 in open-access papers (continued):
Sharing a sentence is not in itself a finding about the gene and the disease.
gastric cancer (7 papers, 2013 to 2024). A primary or metastatic malignant neoplasm involving the stomach. "For instance, it was recently reported that overexpression of CUL1 is associated with poor prognosis of patients with gastric cancer." (PMID 23935076, 2013). "Furthermore, previous studies have shown that downregulation of MAGI1 is associated with poor prognosis of HCC and that overexpression of CUL1 is associated with poor prognosis of patients with gastric cancer." (PMID 24988079, 2014). "On the one hand, inhibition of CUL1 can up-regulate P21 and P27, thus limiting the proliferation of gastric cancer cells." (PMID 37777749, 2023). "CUL1 regulates the biological function of gastric cancer cells through two pathways." (PMID 37777749, 2023). "Here we showed that in gastric cancer cells, MLN4924 rapidly inhibited cullin 1 neddylation and remarkably suppressed growth and survival as well as migration in a dose-and time-dependent manner." (PMID 27063292, 2016). "To further investigate the role of CRL1/SCF in gastric cancer, we first determined the expression levels of three CRL1/SCF E3 components, RBX1, SAG/RBX2 and cullin-1 in several gastric cancer cell lines." (PMID 27063292, 2016).
lung carcinoma (6 papers, 2013 to 2024). "When cullin 1-knockdown A549 lung cancer cells were treated with cycloheximide (CHX), ERK3 protein levels were sustained." (PMID 35022544, 2022). "We next determined the effect of transfected SAG/CUL5 or RBX1/CUL1 on endogenous levels of β-TrCP1 in two lung cancer cell lines, A427 and A549 harboring relatively high levels of β-TrCP1." (PMID 27910872, 2016). "Moreover, cullin 1 knockdown in A549 lung cancer cells elevated ERK3 protein levels." (PMID 35022544, 2022). "The other genes AR, ATF2, CUL1, EP300, GATA4, LEF1, SKP2 in these subnetworks have also been identified as important in lung cancer." (PMID 24369052, 2013). "Thus, CUL1 and UBE2L3 might have double-edged functions for tumor promotion in lung cancer while suppressing HPV+ cancers through E7 degradation." (PMID 38226814, 2024).
colorectal cancer (5 papers, 2020 to 2025). A primary or metastatic malignant neoplasm that affects the colon or rectum. "Melanoma (17.76%), lung cancer (13.16%), endometrioid carcinoma (8.33%), bone cancer (8.2%), colorectal cancer (7.69%), and pancreatic cancer (7.61%) were among the cancers that had relatively high DNA CUL1 DNA amplification." (PMID 37760968, 2023). "A study has reported that the expression of CUL1 in colorectal cancer (CRC) can be valuable molecular markers to predict the prognosis of the CRC patients." (PMID 33344378, 2020). "To further investigate the role of Cullin-1 at the TRAIL-R2 DISC, we assessed its recruitment in a panel of colorectal cancer cell line models with differing degrees of TRAIL sensitivity." (PMID 32313199, 2020).
ovarian carcinoma (4 papers, 2021 to 2024). A malignant neoplasm originating from the surface ovarian epithelium. "In all instances, deep deletions and gene amplifications are extremely rare, generally occurring in <1% of all cancers, except for CUL1 amplifications that occur in ~7% of ovarian cancer cases." (PMID 34445249, 2021). "Collectively, SKP1 copy number losses (shallow and deep deletions) range from 7% to 44% in prostate and ovarian cancers, respectively, while CUL1 and RBX1 losses range from 2% (glioblastoma) to 23% (head and neck) and 10% (prostate) to 80% (ovarian), respectively." (PMID 34445249, 2021). "Moreover, we recently demonstrated that reduced expression of SKP1, CUL1 and RBX1 prevents Cyclin E1 degradation leading to an increase in abundance that induces CIN and promotes cellular transformation in colorectal and ovarian cancer contexts." (PMID 35008511, 2021).
renal cell carcinoma (4 papers, 2018 to 2024). "Several studies have shown that CUL1 is upregulated in many cancers and is associated with poor patient prognosis in various cancers, including gastric, breast, renal cell carcinoma, colorectal, and hepatocellular carcinoma (54, –, 58)." (PMID 38226814, 2024). "CUL1 is a scaffold protein of the ubiquitin E3 ligase Skp1/Cullin1/Rbx1/F-box protein complex, which increased in renal cell carcinoma and promotes cancer cell proliferation, migration, and invasion." (PMID 31086232, 2019). "Analyzing cell cycle-independent effects, we found that MLN4924 prevented the UBE2M-dependent neddylation of cullin 1, as recently observed in renal cell carcinoma, while cisplatin induced a strong decrease in proteasome activity, already reported in non-small cell lung cancer cells." (PMID 35197103, 2022).
chronic obstructive pulmonary disease (3 papers, 2020 to 2024). A chronic and progressive lung disorder characterized by the loss of elasticity of the bronchial tree and the air sacs, destruction of the air sacs wall, thickening of the bronchial wall, and mucous accumulation in the bronchial tree. "This study investigated the role and mechanisms of cullin-1 (CUL1) in chronic obstructive pulmonary disease (COPD)." (PMID 39588388, 2024). "In turn, the inhibition of the two interactions of DDIT3 identified by MuXTalk, CUL1 and EP300, has been shown to reduce fibroblast proliferation in chronic obstructive pulmonary disease (COPD) and IPF." (PMID 37953325, 2024).
hepatocellular carcinoma (3 papers, 2016 to 2024). A malignant tumor that arises from hepatocytes. "More specifically in hepatocellular carcinoma Bel-7402 cells, TRIB2 instability requiresβTRCP and total levels are under the regulation of CUL1." (PMID 27019349, 2016).
osteosarcoma (3 papers, 2017 to 2023). A usually aggressive malignant bone-forming mesenchymal neoplasm, predominantly affecting adolescents and young adults. "Some markers reported to be associated with aggressive osteosarcomas are β4 Integrin, Ezrin, and Cullin-1." (PMID 30576337, 2018). "Among the other six Cullins, only CUL4A was slightly overexpressed (~1.4–1.7-fold induction) in osteosarcoma cells, but not the other five Cullins, including CUL1, CUL2, CUL3, CUL5 and CUL7." (PMID 28446751, 2017).
prostate carcinoma (3 papers, 2013 to 2025). A carcinoma that arises from epithelial cells of the prostate gland. "We analyzed expressions of known p27-targeting E3 ubiquitin ligases, such as CUL1 (cullin 1), SKP1 (S-phase kinase associated-protein 1), and SKP2, in prostate cancer cells." (PMID 40251202, 2025).
alcohol (2 papers, 2018 to 2023). "Thus, based on bioinformatics analysis predicting the interaction between DUSP1 and CUL1, the task of our present research was to figure out whether DUSP1 protects the liver against alcohol-related injury through preventing CUL1-mediated mitophagy suppression." (PMID 37063418, 2023).
breast invasive carcinomas (2 papers, 2018 to 2023). "We used the starBase v3.0 project, which contained the gene expression profiles of 1104 TCGA invasive breast carcinomas, to determine the association between CUL1 with mTOR, and revealed a strong positive correlation between CUL1 and mTOR expression levels (r = 0.195, P = 6.90e-11)." (PMID 37204251, 2023).
glioblastoma (2 papers, 2019 to 2021). The most malignant astrocytic tumor (WHO grade IV). "Conversely, copy number gains (gains plus amplifications) for SKP1, CUL1, and RBX1 range from 3% (uterine) to 31% (liver), 12% (cervical) to 80% (glioblastoma), and 1% (prostate) to 22% (head and neck), respectively." (PMID 34445249, 2021).
head and neck cancer (2 papers, 2024 to 2025). A primary or metastatic malignant neoplasm affecting the head and neck. "Similarly, the membrane-associated ubiquitin ligase MARCHF8 was recently reported to stabilize E7 by degrading the ligases Cullin-1 (CUL-1) and UBE2L3 in head and neck cancer." (PMID 40130877, 2025).
Hyperglycemia (2 papers, 2023 to 2024). An increased concentration of glucose in the blood. "Similar to the results of UCH overexpression, whole-body knockdown of CUL1 using hs-GAL4 driver rescued the hyperglycemia induced by HSD." (PMID 38212312, 2024). "The hyperglycemia in whole-body CUL1 overexpression flies and HSD flies was dramatically rescued by feeding MLN4924 or TAS4464." (PMID 38212312, 2024). "Meanwhile, hinting at the important influence of CUL1 on cell metabolism, pharmacological inhibition of CUL1 neddylation has been reported to reduce hyperglycemia through sensitizing hepatic insulin signaling in mice." (PMID 37063418, 2023). "Additionally, the hyperglycemia of flies expressing CUL1 in the whole body and HSD flies were rescued by UBA3, UBE2M, or RBX1 knockdown." (PMID 38212312, 2024). "In contrast to the results from CUL1 knockdown, knockdown of CUL3 or CUL5 did not improve the hyperglycemia of HSD flies." (PMID 38212312, 2024).
mesothelioma (2 papers, 2015 to 2025). A usually malignant and aggressive neoplasm of the mesothelium which is often associated with exposure to asbestos. "Additionally, mesothelioma is characterized by the frequent loss or mutation of tumor suppressor genes such as cyclin dependent kinase inhibitor 2 A (CDKN2A), BRCA1 associated protein 1 (BAP1), neurofibromin 2 (NF2), and cullin 1 (CUL1)." (PMID 40223054, 2025).
triple-negative breast carcinoma (2 papers, 2016 to 2018). An invasive breast carcinoma which is negative for expression of estrogen receptor (ER), progesterone receptor (PR), and human epidermal growth factor receptor 2 (HER2). "MiR-302a targeted regulated the CUL1 expression and mediated the Selumetinib-induced cytotoxicity of triple-negative breast cancer." (PMID 27769200, 2016). "Moreover, we showed that EZH2 overexpression rescued CUL1 knockdown-decreased transcriptional activities of NF-κB, which is accordant with previous findings that NF-κB activation is critical for cytokines expression and dependent upon high EZH2 expression in triple-negative breast cancer cells." (PMID 30578411, 2018).
3M syndrome (1 paper, 2022). 3M syndrome is a primordial growth disorder characterized by low birth weight, reduced birth length, severe postnatal growth restriction, a spectrum of minor anomalies (including facial dysmorphism) and normal intelligence. "And if so, are there essential functions of FBXW8 explaining lack of disease mutations, and by extension does CUL1 also play a role in 3M syndrome?" (PMID 35982156, 2022).
amebiasis (1 paper, 2021). A parasitic infectious disorder caused by amoebas. "Here we show that Eh in contact with macrophages and colonic epithelial cells activated caspase-1 that cleaved cullin-1/5 in a dose- and time-dependent manner that was replicated in a colonic loop model of intestinal amebiasis." (PMID 34499701, 2021). "To determine if cullin-1/5 was degraded during intestinal amebiasis, we used a short-term mouse colonic loop model of infection and showed significant degradation of neddylated and unneddylated cullin-1 and -5." (PMID 34499701, 2021).
Anxiety (1 paper, 2021). Intense feelings of nervousness, tension, or panic often arise in response to interpersonal stresses. "The results showed that Gfap, Rhog, Gnai2, Ppp1r1b, and Uqcrh were specifically dysregulated in the prefrontal cortex of the depression-susceptible group, while Tubb6, Urod, Cul1, Spred1, and Gpcpd1 were specifically dysregulated in the anxiety-susceptible group." (PMID 33627638, 2021).
asthma (1 paper, 2020). "Therefore, despite evidence from experimental studies, the effect of miR-223 on the target genes IKKα, TRAF6, and CUL1 in asthma and COPD patients, and whether their regulation contributes to the pathogenesis of these diseases, remains unclear." (PMID 32509795, 2020). "For CUL1 and TAB2, it is unknown if there are any differences in expression between asthma, COPD patients, and healthy controls." (PMID 32509795, 2020).
atherosclerosis (1 paper, 2024). A disease characterized by the build-up of fatty material and calcium deposition in the arterial wall resulting in partial or complete occlusion of the arterial lumen.
bladder cancer (1 paper, 2025). "The analysis revealed that UBE2D3 and COPS2 are highly expressed in seven different bladder cancer cell types, whereas HIF3A and CUL1 are expressed at low levels in the same cell clusters." (PMID 40524221, 2025).
cervical cancer (1 paper, 2024). A primary or metastatic malignant neoplasm involving the cervix. "HPV E7 was previously shown to be ubiquitinated and degraded by CUL1 and UBE2L3 in cervical cancer cells." (PMID 38226814, 2024).
colon cancer (1 paper, 2020). "Consistent with that result, Cullins redundantly ubiquitylate the replication licensing factor CDT1, and co-knockdown of CUL1/4A/4B is necessary to mirror MLN4924-induced endoreplication in HCT-116 colon cancer cells." (PMID 32123578, 2020).
COVID-19 (1 paper, 2020). A disease caused by infection with severe acute respiratory syndrome coronavirus 2. "Among our results, several immune-related pathways including those activated by Fc-epsilon-related signaling (LYN and PI3K), NIK/NF-κB (ub, CUL1, SKP1, proteasome, and NFKB2), and via C-type lectin receptor pathways (PTPN11 and CARD9) were enriched in the COVID-19 lungs." (PMID 33060566, 2020).
esophageal squamous cell carcinoma (1 paper, 2024). Esophageal squamous cell carcinoma (ESCC) is a type of esophageal carcinoma (EC) that can affect any part of the esophagus, but is usually located in the upper or middle third. "A recent study showed that membrane-associated ring-CH-type finger 8 (MARCHF8) knockdown in esophageal squamous cell carcinoma cells increases the levels of CUL1 and UBE2L3 proteins." (PMID 38226814, 2024). "By analyzing proteomics data from a previous study in esophageal squamous cell carcinoma, we found that the CUL1 and UBE2L3 proteins are among the cellular proteins increased by the MARCHF8 knockdown." (PMID 38226814, 2024).
Ewing sarcoma (1 paper, 2013). A small round cell tumor that lacks morphologic, immunohistochemical, and electron microscopic evidence of neuroectodermal differentiation. "Importantly, successive steps allowed to identify novel players involved in Ewing sarcoma such as CUL1 or CFLAR or IER3." (PMID 23935076, 2013). "Among these, several necessary connections between ubiquitin proteasome system members (CUL1, SKP1, SKP2, ANAPC2) and EWS-FLI1 were identified, potentially indicating an interesting link between this oncogene and the protein turnover regulation in the context of Ewing sarcoma." (PMID 23935076, 2013). "Therefore, EWS-FLI1 regulation of CUL1 expression may profoundly affect SCF-mediated protein degradation and participate to proliferation and apoptosis deregulation in Ewing sarcoma." (PMID 23935076, 2013).
Hepatic fibrosis (1 paper, 2024). The presence of excessive fibrous connective tissue in the liver. "For instance, in the alcohol-induced OS state, low expression of dual-specificity phosphatase-1 (DUSP1) caused translocation of the E3 ubiquitin ligase component cullin-1 (CUL1) to the nucleus, leading to defective Parkin-mediated mitophagy and triggering hepatic fibrosis." (PMID 39183973, 2024).
Insulin resistance (1 paper, 2024). Increased resistance towards insulin, that is, diminished effectiveness of insulin in reducing blood glucose levels. "However, when overnutrition persists owing to continuous exposure to HSD, CUL1 proteins accumulate in cells and eliminate IRS1 proteins, leading to insulin resistance." (PMID 38212312, 2024). "Based on our findings, we suggest that increased insulin signaling promotes the expression of CUL1, resulting in the breakdown of IRS1 to turn the signaling off temporarily; however, prolonged overnutrition disrupts IRS1 consistently, leading to the development of insulin resistance." (PMID 38212312, 2024).
laryngeal carcinoma (1 paper, 2019). Carcinoma that arises from the laryngeal epithelium. "14‐3‐3ζ negatively regulates senescence in Hep‐2 cells, suggesting that 14‐3‐3ζ targeting may serve to suppress the expansion of laryngeal cancer via induction of senescence through the Cul‐1/SCFSkp2/p27 axis." (PMID 31222857, 2019). "In summary, we have demonstrated that 14‐3‐3ζ silencing significantly induces premature senescence in Hep‐2 laryngeal cancer cells, concomitantly upregulating p27, which is driven from the inactivation of the SCF ubiquitin ligase through the deneddylation of Cul‐1." (PMID 31222857, 2019).
malaria (1 paper, 2024). Malaria is a serious and sometimes fatal disease caused by a parasite that commonly infects a certain type of mosquito which feeds on humans. "To investigate the CRLs of human malaria parasite Plasmodium falciparum, we generated parasites expressing tagged P. falciparum cullin-1 (PfCullin-1), cullin-2 (PfCullin-2), Rbx1 (PfRbx1) and Skp1 (PfSkp1)." (PMID 38416790, 2024).
metastatic melanoma (1 paper, 2012). A melanoma that has spread from its primary site to another anatomic site. "The classification tree results of primary and metastatic melanoma showed that ING4 and Cul1 were on the top of tree structure." (PMID 23028750, 2012). "We analyzed primary and metastatic melanomas separately, the ING4 and Cul1 were the best in the classification tree." (PMID 23028750, 2012).
myeloma (1 paper, 2023). "Studies showed that the knockdown of CUL1 can sensitize or further overcome myeloma cells’ resistance to PIs, highlighting the function of CUL1 in treating MM patients." (PMID 37047654, 2023).
necrotizing enterocolitis (1 paper, 2023). Necrotizing enterocolitis (NEC) is a devastating disease that affects mostly the intestine of premature infants. "The probiotic bacteria Lactobacillus rhamnosus GG (LGG) can induce the production of ROS and consequently inactivate Ubc12 and inhibit the NF-κB signaling pathway through blocking the NEDDylation of Cul1, which contributes to preventing necrotizing enterocolitis (NEC) and relieving IBD in neonates." (PMID 37006236, 2023).
neuroblastoma (1 paper, 2022). Neuroblastoma (NB) is the most common solid, extracranial childhood tumor. "Treatment of M17 neuroblastoma cells (concentrations up to 10 μM) with CuL1, CuL3 and CuL4 did not significantly impact cell health as measured by both assays." (PMID 36142627, 2022).
Obesity (1 paper, 2021). Accumulation of substantial excess body fat. "Moreover, CUL1 (along with SKP1 (S-phase-kinase-associated protein 1) and F-Box protein) forms the largest E3 ubiquitin ligase family (Skp1-Cullin1-F-box (SCF)) E3 ligase is known for controlling obesity with an association of Skp2." (PMID 33669862, 2021).
ovarian tumors (1 paper, 2014). "To assess the possibility that alteration to these components may be contributing to NRF2 activation in ovarian tumors, we evaluated DNA-level alterations affecting the genes involved in this BTRC/SKP1/CUL1 complex." (PMID 25114896, 2014).
psoriasis (1 paper, 2023). An autoimmune condition characterized by red, well-delineated plaques with silvery scales that are usually on the extensor surfaces and scalp. "A study based on the microarray data of a cDNA library indicated that Cul1 is highly associated with the development of psoriasis." (PMID 37006236, 2023).
renal carcinoma (1 paper, 2017). A carcinoma arising from the epithelium of the renal parenchyma or the renal pelvis. "Furthermore, knockdown of Cul1 suppresses renal cancer cell migration and invasion abilities by up-regulating the expression of TIMP-1and inhibit the expression of MMP-9." (PMID 28108731, 2017).
schizophrenia (1 paper, 2023). A major psychotic disorder characterized by abnormalities in the perception or expression of reality. "Also, a large-scale exome sequencing study identified single genes whose rare mutations substantially increase the risk for schizophrenia, of which six genes (SETD1A, CUL1, XPO7, GRIA3, GRIN2A, and RB1CC1) showed odds ratios larger than ten." (PMID 36878965, 2023).